MC1R (melanocortin 1 receptor)
Diseases named in the same sentence as MC1R in open-access papers (continued):
Sharing a sentence is not in itself a finding about the gene and the disease.
skin cancer (continued). "There was no intervention effect on skin cancer worry in either MC1R average-risk (P = 0.59) or higher-risk (P = 0.62) participants, and no changes in skin cancer worry between baseline and post-intervention within each arm (all P > 0.05)." (PMID 35845857, 2022). "MC1R is pleiotropic for Category A Phenotypes (skin wrinkling and sagging phenotype), Category B Phenotypes (skin colour phenotype), Category C Phenotypes (skin cancer phenotype), and Category D Phenotypes (skin global impression phenotypes)." (PMID 35907981, 2022). "Given that MC1R also predisposes to NMSC, patients may be interested in the implications for genetic risk for a range of skin cancer types." (PMID 35959144, 2022). "Precision prevention incorporating genetic testing for (melanocortin-1 receptor) MC1R, a skin cancer susceptibility marker, may improve prevention behavior." (PMID 35845857, 2022). "Among those who had never been screened, only those with a family history of skin cancer and higher risk MC1R, or those with no family history of skin cancer and average risk MC1R, completed any screening at follow up." (PMID 34439206, 2021). "Interestingly, previous studies explored the role of MC1R as a prognostic marker in metastatic melanoma and as a potential approach for target treatments in skin cancers." (PMID 34356109, 2021). "Currently, our understanding of MC1R variants and their association with skin cancer risk is based on studies predominately in non-Hispanic whites." (PMID 32350296, 2020). "Interestingly, tubulin beta-3 was identified as a direct downstream protein of human melanocortin 1 receptor (MC1R), a protein associated to skin pigmentation, ultraviolet radiation, and to other aspects such as skin cancers." (PMID 28626498, 2017). "Certain MC1R polymorphisms are responsible for the red hair color (RHC) phenotype (red hair, fair skin and poor tanning response) which is associated with high UV-radiation sensitivity and skin cancer susceptibility (CM and NMSC)." (PMID 24742402, 2014). "In humans, MC-1R is known to account for substantial variation in skin cancer incidence." (PMID 20126537, 2010). "In addition, MC1R antagonists and agonists might be employed as potential therapeutic drugs for skin cancer." (PMID 35872794, 2022). "The human MC1R locus contains polymorphisms, with non-functional MC1R mutants associated with red-haired, fair-skin individuals, a poor tanning response and increased risk of developing skin cancers." (PMID 33861845, 2021). "However, to the best of our knowledge, studies of associations between MC1R and skin cancer risk in Hispanic populations are lacking." (PMID 32350296, 2020). "We found that RHC MC1R skins cells differ from wild-type in the deregulation of genes involved in key physiological processes such as differentiation, cell adhesion and cell cycle progression which may be directly related to the etiology of skin cancer." (PMID 24742402, 2014). "If loss-of-function mutations in MC1R are proven to protect canines from SCCD, it may initially seem to be a surprising result, as loss-of-function MC1R variants are associated with increased incidence of skin cancer in humans." (PMID 23555311, 2013). "Indeed, a larger cohort or epidemiologic studies are needed to scrutinize whether treatment of skin cancer with α-MSH or other more stable agonists of MC-1R might potentially lead to an improvement of anti-tumoral immune responses." (PMID 20126537, 2010). "Therefore, treatment of contact allergies or skin cancer with alpha-melanocyte-stimulating hormone or other more stable agonists of melanocortin-1 receptor might ameliorate disease or improve antitumoral immune responses." (PMID 20126537, 2010). "Furthermore, our results might represent a missing link between the yet unknown role of MC-1R in cutaneous biology and the influence of MC-1R in skin cancer development." (PMID 20126537, 2010).
skin cancer (continued). "However, most genetic epidemiology studies of skin cancer to date have focused on non-Hispanic white populations, which potentially limits the generalizability of skin cancer risk information based on MC1R genotypes to at-risk populations with more diverse genetic ancestry, such as Hispanics." (PMID 32350296, 2020). "Firstly, when we compared the genetic correlation, and the MTAG results before and after excluding genomic regions (HLA, ASIP, IRF4, MC1R, SLC45A2 and CDKN2A) with very large effect sizes for skin cancers and pigmentation traits, and there was a high concordance." (PMID 36496446, 2022). "Further, skin cancer worry was not increased by MC1R testing." (PMID 34439206, 2021). "However, the impact of MC1R testing on skin cancer awareness and sun avoidance behavior has not been established yet." (PMID 34356109, 2021). "However, MC1R has not been employed as a target treatment for skin cancers in humans so far." (PMID 34356109, 2021). "However, our study is not the only one to suggest that functionally active MC1R signaling may promote rather than protect against skin cancer incidence/progression." (PMID 23555311, 2013).
melanism (31 papers, 2008 to 2025). "For instance, a study on Javanese women found that the heterozygote Val92Met polymorphism of the Melanocortin-1 Receptor (MC1R) gene was significantly associated with the incidence of melasma." (PMID 41154805, 2025). "Melanism is typically caused by mutations in one of two regulatory genes: the Melanocortin 1 Receptor (MC1R) or the Agouti Signaling Protein (ASIP)." (PMID 38396615, 2024). "Mutations in the coding portions of either MC1R or ASIP have been tied to melanism in lizards, birds, and many different groups of mammals." (PMID 38396615, 2024). "Melanism, for example, has repeatedly evolved in mammals due to dominant and semidominant mutations in the Mc1r locus which have become fixed." (PMID 37902626, 2023). "Sequence variations in the melanocortin‐1 receptor (MC1R) gene are associated with melanism in different animal species." (PMID 35451516, 2022). "Non-synonymous mutations at the MC1R pigmentation gene are associated with melanism on SA/SC, while ASIP, an antagonistic ligand of MC1R, is associated with melanism on Ugi." (PMID 36318577, 2022). "An MC1R allele with the same 24 bp deletion was previously found to be associated with melanism in the gray squirrel." (PMID 31296164, 2019). "An allele at the MC1R locus with a 24 bp deletion (MC1R∆24) is associated with melanism in colour group 1 (orange agouti) fox squirrels from Colorado and Nebraska." (PMID 31296164, 2019). "In wild populations, mutations in MC1R have been associated with melanism in lizards, ~ 10 species of birds and a variety of mammals, from rodents to cats." (PMID 31296164, 2019). "In laboratory mice, for example, mutations in alleles of Mc1r leads to dominant melanism, whereas mutations in alleles of Agouti usually cause recessive melanism." (PMID 31119086, 2019). "One persistent result evolving from most studies is the contribution of the MC1R coding region in explanation of melanism variation, sometimes displaying shared mutations due to convergent evolution between coldly related species." (PMID 28770057, 2017). "(Additional, less frequent causes of melanism in some mammals include mutations of beta-defensin 103 [an alternative ligand for MC1R], Attractin [an accessory receptor for ASIP], or Mahogunin [an E3 ubiquitin ligase that acts upstream of the MC1R])." (PMID 25695801, 2015). "One recurrent result emerging from most studies is the involvement of the melanocortin-1 receptor (MC1R) coding region in explaining variation in melanism, sometimes showing shared mutations due to convergent evolution between distantly related species." (PMID 23227219, 2012). "This candidate gene approach has been applied successfully to discover the genetic basis of melanism in mammals and other vertebrates, implicating several different mutations within the melanocortin-1-receptor gene (Mc1r)." (PMID 20526362, 2010). "To determine if the same gene and same mutation was responsible for melanism in other populations of P. maniculatus, we sequenced both Mc1r and Agouti in melanic and wild type mice from an additional population." (PMID 19649329, 2009). "The Agouti sequence possesses neither the aQ65term nor the aΔ125kb mutation, nor does it contain any obvious melanism-causing mutations in Mc1r, demonstrating a third independent origin of melanism in P. maniculatus." (PMID 19649329, 2009). "In captive vertebrates, spontaneous mutants of Agouti, Mc1r, Mgrn, and Atrn have all been found to cause melanism [e.g.]." (PMID 19649329, 2009). "Our primary aim was to examine the hypothesis that geographic variation in degree of melanism is associated with different MC1R alleles that are functionally associated with differences in melanin production." (PMID 33095228, 2020).
melanism (continued). "In a western population, melanism is associated with a 24 bp deletion in the melanocortin-1-receptor gene (MC1RΔ24 allele), whereas in a south-eastern population, melanism is associated with a point substitution in the agouti signalling protein gene causing a Gly121Cys mutation." (PMID 31296164, 2019). "Having found that the same 24 bp deletion in the MC1R, which had previously been described in the gray squirrel, was also associated with melanism in the colour group 1 (orange agouti) fox squirrel, the study was expanded to examine the causes of derived allele sharing between the two species." (PMID 31296164, 2019). "Consistent with the nature of the mutations, melanism caused by MC1R mutations is dominantly inherited, while melanism caused by ASIP mutations is recessively inherited; however, the inheritance pattern of melanism in pampas, Geoffroy’s cat, and the kodkod is not known." (PMID 25695801, 2015). "We identify mutations of Agouti signaling protein (ASIP) or the Melanocortin 1 receptor (MC1R) as independent causes of melanism in three closely related South American species: the pampas cat (Leopardus colocolo), the kodkod (Leopardus guigna), and Geoffroy’s cat (Leopardus geoffroyi)." (PMID 25695801, 2015). "In Geoffroy’s cat, we identified an MC1R mutation as the likely cause of melanism." (PMID 25695801, 2015). "Thus, collectively, these results suggest that the ECL1 of MC1R indeed is of importance and, in some cases, associated with melanism." (PMID 21931793, 2011). "Thus, it is unclear why Mc1r has repeatedly been shown to be associated with melanism in nature and a key question is: are melanism-inducing mutations in Agouti not found because they occur less often, or are they simply more difficult to detect?" (PMID 19649329, 2009). "Therefore, the gain of function in MC1R or the loss of function in ASIP induces melanism." (PMID 37440497, 2023). "Therefore, gain of function in MC1R or loss of function in ASIP induce melanism." (PMID 23251368, 2012). "Thus, if melanic phenotypes are often fixed from new dominant mutations rather than standing genetic variation, this may explain the prevalence of melanism caused by Mc1r." (PMID 19649329, 2009). "A charge-changing mutation at the position homologous to 92 (E92K) is associated with melanism in mice, chicken, quail and bananaquit (Coereba flaveola) and in vitro studies in mouse and chicken have shown that the mutation causes constitutive activation of MC1R." (PMID 18789136, 2008). "The correlation between Val92Met and Arg163Gln genotypes of Melanocortin-1 Receptor (MC1R) gene and the incidence of melasma was assessed in Indonesian women." (PMID 38628650, 2024). "We sequenced the MC1R and ASIP genes for five wild-type and seven melanistic S. aberti individuals to search for melanism-associated mutations." (PMID 38396615, 2024). "This novel mutation is different than the 24 base pair deletion in MC1R previously documented in S. carolinensis and western S. niger and the single base pair mutation in ASIP causing melanism in southeastern S. niger." (PMID 38396615, 2024). "Our study identifies variation in the degree of melanism that can be explained by four or fewer MC1R substitutions." (PMID 33095228, 2020). "This includes mutations in the melanocortin 1 receptor (MC1R; associated with melanism,), MC4R (obesity,), the ghrelin receptor (short stature,) and rhodopsin (retinitis pigmentosa,) among others." (PMID 22899926, 2012). "We discuss these findings in the context of the evolution of melanism, as well as the relative roles of ASIP and MC1R in the origin of such pigmentation variants." (PMID 23251368, 2012). "Another example of recessive melanism determined by an in-frame deletion in the MC1R gene has been recently reported in guinea fowl." (PMID 20594318, 2010).
melanism (continued). "Mc1r mutants represent the vast majority of cases of melanism in natural populations of mammals, despite many occurrences of melanic Agouti mutants in captive and domestic stocks." (PMID 19649329, 2009). "Here, we focus on Mc1r and Agouti because their interaction has been well characterized in the lab mouse and thus can be extended to the study of melanism in other taxa." (PMID 19649329, 2009). "Sequencing of Agouti and Mc1r coding regions in melanic individuals from other geographic locations shows that melanism arose independently at least three times in P. maniculatus." (PMID 19649329, 2009). "The alternative was that there were no functional differences between MC1R alleles across populations with different degrees of melanism." (PMID 33095228, 2020). "In contrast, colour group 2 (gray/tan agouti) fox squirrels do not show an association between MC1R and melanism (which was the basis of our previous report of a lack of association), and the MC1R∆24 allele is absent in this population." (PMID 31296164, 2019). "High activity of the MC1R protein leads to enhanced synthesis of eumelanin, a process that is inhibited by ASIP, so that gain-of-function mutations of MC1R or loss-of-function mutations in ASIP lead to melanism." (PMID 31296164, 2019). "The most common causes of melanism mutations are gain-of-function alterations in MC1R, or loss-of-function alterations in ASIP, which encodes Agouti signaling protein, a paracrine signaling molecule that inhibits MC1R signaling." (PMID 25695801, 2015). "No other ASIP coding sequence variants were identified in the pampas cat or in the kodkod; four intraspecific variants in MC1R were present in the pampas cat, but none of them exhibited an association with melanism." (PMID 25695801, 2015). "One MC1R allele determined by a nonframeshift deletion associated only with melanism has been observed in each of other four species (jaguar, jaguarundi, squirrel and guinea fowl)." (PMID 20594318, 2010). "The melanic individual from Michigan possesses neither the aΔ125kb allele nor the aQ65term allele; melanism in this population must be caused either by variation at another locus or possibly by unexamined variation at the Agouti or Mc1r loci." (PMID 19649329, 2009). "Our result suggests that G104S substitution could decrease MC1R activity and hence it is not likely to be causative for the melanism." (PMID 35534524, 2022). "TYRP1, MC1R, and GPR143 genes are thought to play an important role in the process of melanosis in chickens." (PMID 37235424, 2023). "In mammals and birds, many cases of melanism are caused by amino acid substitutions in the Melanocortin 1 receptor, which controls the shift from pheomelanin to eumelanin production in melanocytes, although cases in which Melanocortin 1 receptor is not implicated have been reported." (PMID 25168010, 2014). "For the pampas cat and Geoffroy’s cat, chromosomes bearing melanism mutations (ASIP for pampas cat, MC1R for Geoffroy’s cat) do not cluster together; for the kodkod, there is some clustering of melanistic ASIP chromosomes that may reflect recent population history." (PMID 25695801, 2015).
cutaneous melanoma (27 papers, 2003 to 2025). A primary melanoma arising from atypical melanocytes in the skin. "Inherited genetic variability in the melanocortin 1 receptor (MC1R) gene is a well‐known determinant for the risk of cutaneous melanoma." (PMID 40926353, 2025). "In a study in the Swedish population, 33% of the healthy Swedish population had at least one MC1R R allele, whereas the corresponding number for patients diagnosed with primary cutaneous melanoma was 54%." (PMID 40926353, 2025). "It was demonstrated that individuals carrying a single MC1R variant exhibit 1.41 higher odds (95% CI: 1.07–1.87) of developing sporadic cutaneous melanoma compared with wildtype homozygous subjects." (PMID 38473375, 2024). "Higher MC1R is also seen in deeper (>1 mm) primary lesions, ulcerated lesions, and mucosal melanomas compared to cutaneous melanomas and was associated with shorter survival in primary and metastatic tumors." (PMID 39171057, 2024). "Higher MC1R expression was seen in deeper (>1 mm) primary lesions, ulcerated lesions, and mucosal melanomas compared to cutaneous melanomas and was associated with shorter survival in primary and metastatic tumors." (PMID 37790306, 2023). "The major genetic determinants of cutaneous melanoma risk in the general population are disruptive variants (R alleles) in the melanocortin 1 receptor (MC1R) gene." (PMID 27403562, 2016). "Germline mutations in CDKN2A and/or red hair color variants in MC1R genes are associated with an increased susceptibility to develop cutaneous melanoma or non melanoma skin cancer." (PMID 24742402, 2014). "Melanocortin-1 receptor polymorphisms have been associated with red hair and fair skin, and also with cutaneous melanoma in humans." (PMID 14612916, 2003). "Moreover, carriers with two or more MC1R variants demonstrated 2.51 increased odds (95% CI: 1.83–3.44) of developing cutaneous melanoma." (PMID 38473375, 2024). "Furthermore, variants in the MC1R region have been shown to be strongly associated with higher susceptibility of cutaneous melanoma." (PMID 36536295, 2022). "In fact, about 15 % of all cases of cutaneous melanoma are associated with some MC1R variants." (PMID 26850723, 2016). "Finally, our study confirmed the association of some MC1R gene variants with the occurrence of cutaneous melanoma as previously reported." (PMID 19799798, 2009). "Variants of the melanocortin-1 receptor (MC1R) gene have been linked to sun-sensitive skin types and hair colour, and may independently play a role in susceptibility to cutaneous melanoma." (PMID 14612910, 2003). "Interestingly, the frequency of MC1R R alleles in this cohort of Swedish patients with metastatic melanoma was lower than has been demonstrated for Swedish patients diagnosed with primary cutaneous melanoma (38% vs. 54%)." (PMID 40926353, 2025). "Variants in genes of low to moderate penetrance related to skin pigmentation and differentiation of melanocytes, such as the MC1R and MITF genes, are also of great importance in determining the risk for cutaneous melanoma." (PMID 37895483, 2023). "This analysis revealed a subset of skin cutaneous melanomas (SKCM) with MC1R expression higher than any other cancer types or normal tissues." (PMID 37714844, 2023). "The MC1R gene (melanocortin-1 receptor) is one of the main low/moderate penetrance genes related to cutaneous melanoma." (PMID 35085295, 2022). "Data from 10,389 adult cancers from the Cancer Genome Atlas (TCGA) dataset were first used to compare the common and rare MC1R variant allele frequencies in PM and AHM samples in the 470 SKCM (Skin Cutaneous Melanoma) collection." (PMID 32966289, 2020). "For individuals with the RHC phenotype, the risk of cutaneous melanoma was not independently predicted by having MC1R variants." (PMID 38473375, 2024). "A recent polled analysis showed that the presence of any MC1R variant confers a 60% higher risk for cutaneous melanoma to carriers when compared to noncarriers." (PMID 37958811, 2023).